TRMT10B (tRNA methyltransferase 10B)
Description:
S-adenosyl-L-methionine-dependent guanine N(1)- methyltransferase that catalyzes the formation of N(1)-methylguanine at position 9 (m1G9) in tRNAs. Probably not able to catalyze formation of N(1)-methyladenine at position 9 (m1A9) in tRNAs.
Synonyms: RG9MTD3; FLJ31455; bA3J10.9
Tractability: Antibody: the Human Protein Atlas places it where antibodies can reach.
Gene: Protein-coding gene on chromosome 9 (37,753,774 to 37,778,972, forward strand). Ensembl gene ENSG00000165275.
Subcellular location (Human Protein Atlas): Nucleoplasm; Plasma membrane
Gene Ontology:
Molecular function: protein binding; tRNA (guanosine(9)-N1)-methyltransferase activity; tRNA binding
Biological process: tRNA N1-guanine methylation
Cellular component: cytosol; nucleoplasm; nucleus
Genetic constraint (gnomAD): Loss-of-function variants: 31 observed, 43.06 expected, observed/expected ratio (o/e) 0.72, 90% interval 0.54 to 0.97. The upper end of that interval is the gene's LOEUF score, 0.97, which puts it in group 4 of 6, group 1 being the genes least tolerant of losing a copy. Missense variants: 360 observed, 374.7 expected, observed/expected ratio (o/e) 0.96, 90% interval 0.88 to 1.05. Synonymous variants: 137 observed, 134.88 expected, observed/expected ratio (o/e) 1.02, 90% interval 0.88 to 1.17.
Homologues: Orthologues: chimpanzee TRMT10B (99% identical), macaque TRMT10B (96% identical), dog TRMT10B (87% identical), rabbit TRMT10B (86% identical), pig TRMT10B (85% identical), guinea pig TRMT10B (84% identical), mouse Trmt10b (78% identical), rat Trmt10b (77% identical), tropical clawed frog trmt10b (62% identical), zebrafish trmt10b (49% identical). Paralogues in human: TRMT10A (26% identical), TRMT10C (22% identical).
Diseases named in the same sentence as TRMT10B in open-access papers:
TRMT10B is named in the same sentence as 1 disease in open-access papers, as found by Europe PMC text mining. Sharing a sentence is not in itself a finding about the gene and the disease. The quoted sentences say what the papers report.
chronic myelogenous leukemia (1 paper, 2020). "Two KO clones for TRMT10A (here abbreviated ΔA4 and ΔA10) and two for TRMT10B (ΔB4 and ΔB9) were generated by a commercial supplier in HAP1 cells, a nearly-haploid human cell line derived from the chronic myelogenous leukemia cell line KBM-7." (PMID 32392304, 2020).